CACNA1C (calcium voltage-gated channel subunit alpha1 C)
Diseases named in the same sentence as CACNA1C in open-access papers (continued):
Sharing a sentence is not in itself a finding about the gene and the disease.
Anxiety (42 papers, 2014 to 2026). Intense feelings of nervousness, tension, or panic often arise in response to interpersonal stresses. "We show evidence of a dysregulation of the HPA axis in unstressed males with reduced dosage of Cacna1c, a gene well established to be linked to an increased risk for neuropsychiatric disorders, and an associated anxiety phenotype." (PMID 40565009, 2025). "Chronic social stress in adulthood increases the susceptibility to developing anxiety‐like behaviors in Cacna1c heterozygous mice and lowers Cacna1c expression in WT." (PMID 40263772, 2025). "Cell-restrictive Cacna1c deletion models help identify the locus of anxiety dysregulation and other functional impacts of altered Cav1.2 levels, as well as underlying neural mechanisms, such as the E/I balance." (PMID 40565009, 2025). "This sensitivity in Cacna1c+/− rodents parallels the observation that women with CACNA1C risk variants are more prone to mood disorders and anxiety than men." (PMID 40565009, 2025). "The CACNA1C variant rs1205787230 was associated with clinical anxiety (a HADS-A score of ≥11 points)." (PMID 38328521, 2023). "The primary purpose was to evaluate a possible association between anxiety and the rs1006737 polymorphism in the CACNA1C gene in depressive patients." (PMID 36238190, 2022). "Genetic variations in CACNA1C are associated with multiple forms of neuropsychiatric diseases linked to stress and anxiety." (PMID 34122501, 2021). "CACNA1C has previously been implicated to be involved in anxiety, cognition, fear conditioning, and depressive phenotypes." (PMID 33076578, 2020). "Genetic variations in CACNA1C, which encodes the Cav1.2 subunit of L-type calcium channels (LTCCs), are associated with multiple forms of neuropsychiatric disease that manifest high anxiety in patients." (PMID 27066530, 2016). "Aberrant postnatal hippocampal neurogenesis and CACNA1C mutations are associated with neuropsychiatric diseases manifesting high anxiety, and mice deficient in Cav1.2 neuronal expression display high anxiety-like behavior." (PMID 27066530, 2016). "Embryonic deletion of Cacna1c in postmitotic forebrain glutamatergic neurons (Nex-Cre) promotes neuropsychiatric disorder-associated phenotypes, such as cognitive decline, impaired synaptic plasticity, reduced sociability, hyperactivity, and increased anxiety." (PMID 36803254, 2023). "Since CACNA1C is a prominent risk factor for many psychiatric disorders, which often go along with heightened stress or anxiety levels, it is interesting to see that a heterozygous knockout of the gene in rats also leads to an altered reaction to stress at the level of the heart." (PMID 37372947, 2023). "Our results demonstrate that spatial memory, hippocampal plasticity and anxiety-related behavior are differentially affected by the loss of Cacna1c from excitatory circuits depending on whether it is deleted during embryonic development or adulthood." (PMID 28696432, 2018). "Notably, anxiety is a prominent component of all forms of neuropsychiatric illness in which CACNA1C has been implicated." (PMID 27066530, 2016). "The other major issue raised by the reviewers is that the impact of this paper would be significantly enhanced if the authors had carried out behavioral studies to test if P7C3-A20 were sufficient to also rescue behavioral effects of loss of cacna1c on any pathological outcome (for example anxiety)." (PMID 27066530, 2016). "Contrasting anxiety phenotypes have also been found in mice haploinsufficient for the SZ/BD risk gene CACNA1c and in mice heterozygous for the BD associated gene Ank3 showing altered behavior in elevated plus maze and light-dark preference but not in the open field test." (PMID 25340473, 2014). "Similarly, mice with heterozygous loss of Cacna1c show anxiety-like phenotype, impaired social behavior, learning, and memory but mice with Cacna1c deleted in adult forebrain glutamatergic neurons only exhibit anxiety-like phenotype and social deficits." (PMID 36803254, 2023).
Anxiety (continued). "Some clinical and animal studies have also found a significant interaction between sex and Cacna1c genotype; for instance, female, but not male, Cacna1c heterozygous mice have been shown to display decreased risk-taking behavior and increased anxiety in multiple tests." (PMID 31031589, 2019). "Finally, we assessed the moderating influence of candidate genes whose level of methylation is associated with the Nr3c1 genotype on anxiety-like behavior: Ank3, Avp, Avpr1a, Avpr1b, Bdnf, Cacna1c, Cyp11b1, Cyp11b2, Fkbp5, Hsd11b1, Igf2, Morc1, Nr3c1, Oxt, Oxtr, Pclo, Slc6a4." (PMID 30655507, 2019). "For example, deletion of Cacna1c, which encodes the Cav1.2 subunit of L-type calcium channels, causes increased cell death of hippocampal neurons in knockout mice and mice harboring forebrain-specific conditional knockout of Cacna1c display unusually high anxiety-like behavior." (PMID 28751711, 2017). "In the EPM test, only female Cacna1c+/− rats showed increased anxiety, spending less time in the open arms." (PMID 40565009, 2025). "Future studies using optimised experimental conditions for OF and EPM will give a more accurate estimate of the magnitude of the change in anxiety in the Cacna1c+/− rats." (PMID 40565009, 2025). "Pre‐pubertal stress in rats leads to anxiety‐like behavior and reduced Cacna1c expression in adulthood." (PMID 40263772, 2025). "These expectations were based specifically on the fact that the JS procedure we used has been shown to impact anxiety and learning, as well as producing a decrease in the expression of Cacna1c itself." (PMID 40263772, 2025). "Future studies should consider oestrous stage to better understand sex differences in bioavailable corticosterone and anxiety behaviour in Cacna1c+/− rats." (PMID 40565009, 2025). "In the OF, Cacna1c+/− rats showed more anxiety-like behaviour, where they spent less time in the open central region of the arena." (PMID 40565009, 2025). "In rodent studies, knockout of Cacna1C in hippocampal and cortical neurons, 5-HT neuron-specific Cacna1C knockout, and Cacna1C heterozygous mice (Cacna1C ±) all exhibit anxiety-like behaviors." (PMID 39268349, 2024). "A recent study showed that impaired expression of CACNA1C disrupts spontaneous Ca2+ activity, leading to abnormal brain development and increased anxiety." (PMID 38328521, 2023). "Conditional deletion of CACNA1C in the hippocampus and cortex resulted in the impairment of spatial memory and increased anxiety like behaviour." (PMID 35013113, 2022). "In this regard, deletion of Cacna1c in mice induces the expression of anxiety‐like behaviors and has an anti‐depressant effect, while in rats it was shown to impair social behavior." (PMID 35969184, 2022). "Constitutive Cacna1c heterozygous knockout (KO) mice, forebrain-specific conditional Cacna1c KO mice, and prefrontal cortex-specific Cacna1c knockdown mice show increased anxiety-like behavior in the elevated-plus maze test." (PMID 33644051, 2021). "Knockout mice for CACNA1C display traits that resemble symptoms of mental disorders and autism such as cognitive decline, anxiety, hyperactivity, decreased sociability, decreased synaptic plasticity." (PMID 31718593, 2019). "Conversely, 4 weeks of chronic unpredictable stress induced depressive- and anxiety-like behavior in both Cacna1c heterozygous mice and their wildtype littermates when assessed 1–2 days following stress." (PMID 31708752, 2019). "Conditional knockout of CACNA1C in forebrain neurons during development results in anxiety in adult mice, whereas knockout of CACNA1C during adulthood does not." (PMID 31805042, 2019). "Sociability, immobility in the FST and spatial object recognition memory were not differentially affected by CSDS, suggesting a specific impact of the interaction between Cacna1c and chronic stress on anxiety." (PMID 28696432, 2018).
Anxiety (continued). "In parallel, mice harboring forebrain-specific conditional knockout of cacna1c (forebrain-Cav1.2 cKO) display unusually high anxiety-like behavior." (PMID 27066530, 2016). "Specifically, mice harboring forebrain-specific conditional knockout of cacna1c (forebrain-Cav1.2 cKO) show elevated anxiety-like behavior in the light/dark conflict test, the open-field test, and the elevated plus maze." (PMID 27066530, 2016). "Constitutive CACNA1C heterozygous mice, forebrain-specific conditional CACNA1C knockout (KO) mice, and prefrontal cortex-specific CACNA1C knockdown mice show increased anxiety-like behavior in the elevated plus maze." (PMID 26136667, 2015). "Evidence for increased innate anxiety responses were also observed in the Cacna1c+/− rat model." (PMID 40565009, 2025). "Increased plasma corticosterone levels in Cacna1c+/− rats may contribute to their heightened anxiety response, as corticosterone treatment and HPA activation are linked to anxiety-like behaviours in rodents." (PMID 40565009, 2025). "Cacna1c+/− rats exhibit evidence of increased anxiety-like behaviours compared to WT rats." (PMID 40565009, 2025). "However, Ehlinger and Commons also confirmed that selective deletion of Cacna1C can increase immobility time in the forced swim test and anxiety levels in the open field test." (PMID 39268349, 2024). "Furthermore, previous studies revealed deficits in the pro-social behavior of Cacna1c+/− rats and, in the mouse model, behavior suggestive of heightened anxiety levels and altered stress response." (PMID 37372947, 2023). "Moreover animal models with genetic variation in CACNA1C has revealed potential alterations in social interactions and increased anxiety along with cognitive disabilities." (PMID 35013113, 2022). "Induced local knockdown of CaCNA1C in the adult PFC is sufficient to induce anxiety-like behavior, and, in this animal model, PFC neurons exhibit lower depression-related protein (REDD1) expression levels, and restoring these levels is enough to reverse the antidepressant-like phenotype." (PMID 33291797, 2020). "In contrast to a developmental inactivation, deletion of Cacna1c from forebrain glutamatergic neurons during adulthood blocked the adverse effects of CSDS on anxiety, enhanced LTP and improved hippocampus-dependent cognitive flexibility during the WCM, without affecting long-term memory." (PMID 28696432, 2018). "In view of the partially opposing effects of Cacna1c on anxiety and cognition during development and adulthood, we wondered whether stress vulnerability would also be differentially affected upon deletion of the calcium channel in adulthood." (PMID 28696432, 2018). "Thus, Cacna1c+/− rats showed evidence of increased anxiety in two tests." (PMID 40565009, 2025). "Here we show that embryonic deletion of Cacna1c in forebrain glutamatergic neurons promotes the manifestation of endophenotypes related to psychiatric disorders including cognitive decline, impaired synaptic plasticity, reduced sociability, hyperactivity and increased anxiety." (PMID 28696432, 2018). "Moreover, embryonic deletion of CACNA1C in glutamatergic neurons in the forebrain promotes the manifestation of endophenotypes related to psychiatric disorders, including cognitive decline, impaired synaptic plasticity, reduced sociability, hyperactivity, and increased anxiety." (PMID 39228919, 2024). "Genes like CACNA1C (calcium regulation) and AHR (inflammation) may influence pain pathways, while NOTCH3 is involved in immune responses and stress regulation, and anxiety may contribute to pain modulation." (PMID 39940809, 2025). "For instance, global Cacna1c haploinsufficiency models and those with conditional knockout in excitatory neurons, especially in the PFC or D1R-expressing neurons, show increased anxiety-like behaviours." (PMID 40565009, 2025).
Anxiety (continued). "It is also important to note that Cacna1c+/− rats had no greater baseline fear or anxiety levels, as indicated by the lack of freezing response at Baseline and Novel Baseline." (PMID 31910256, 2020). "The detection of CACNA1C rs1205787230 supports the hypothesis that calcium channels are involved in the development of increased anxiety in non-psychiatric patients." (PMID 38328521, 2023). "Neither the Cacna1c genotype nor miR‐499‐5p had an impact on the time rats spent in the open arm of the EPM or on their total entries into the open arms (Fig EV4D), indicating that anxiety‐related behavior was not affected by miR‐499‐5p overexpression." (PMID 35969184, 2022).
autism (42 papers, 2011 to 2026). Persistent deficits in social interaction and communication and interaction as well as a markedly restricted repertoire of activity and interest as well as repetitive patterns of behavior. "An understanding of these mechanisms will be critical to our understanding of how variants in CACNA1C give rise to the axonal defects that underlie autism." (PMID 33829152, 2021). "Further work exploring the molecular mechanisms that underlie these perturbations in neuronal polarity and axon termination will give us better understanding of how variants in CACNA1C contribute to the axonal defects that underlie autism." (PMID 33829152, 2021). "Because common variants of CACNA1C are associated with autism, it is likely that this mechanism will be broadly applicable to autism in humans." (PMID 31805042, 2019). "Both common and rare variants in the human CACNA1C gene have been associated with autism and other neurodevelopmental disorders." (PMID 31805042, 2019). "For example, the A genotype at the rs1006737 locus in CACNA1C confers risk for autism and is present in about 33% of the human population." (PMID 31805042, 2019). "For example, genome wide association studies (GWAS) have associated common variants in CACNA1C to autism." (PMID 31805042, 2019). "Our results identified a nominal significant association between two SNPs (rs1006737 and rs4765905) in CACNA1C and autism in 553 nuclear families of Chinese Han ancestry." (PMID 26204268, 2015). "To investigate the association between single nucleotide polymorphisms (SNP) in CACNA1C and autism, we first performed a family-based association study between eighteen SNPs in CACNA1C and autism in 239 trios." (PMID 26204268, 2015). "Furthermore, gain-of-function mutations in CACNA1C can lead to Timothy syndrome, a genetic disease comprising autism spectrum symptoms, arrhythmias and heart disease, Brugada syndrome, long QT syndrome, and early repolarization syndrome." (PMID 37372947, 2023). "Moreover, statistical analysis of whole genome sequencing data indicates that rare variants in CACNA1C are also associated with autism." (PMID 31805042, 2019). "Alternatively, a weak loss of function in CACNA1C could synergize with a weak loss-of-function in WDFY3 to give rise to autism." (PMID 31805042, 2019). "Moreover, haplotype analyses indicated statistically significant association between CACNA1C and autism." (PMID 26204268, 2015). "CACNA1C might potentially be related to alternations in intracellular calcium homeostasis and then confer risk of autism." (PMID 26204268, 2015). "In addition, further studies are necessary to understand the underlying mechanisms the gene CACNA1C exerts on autism as well as other psychiatric disorders." (PMID 26204268, 2015). "To investigate whether the genetic variants in CACNA1C are associated with autism, we performed a family based association study between CACNA1C and autism in Chinese Han population." (PMID 26204268, 2015). "To test whether CACNA1C is involved in the etiology of autism, we performed a family based association study." (PMID 26204268, 2015). "Results of family-based association test between 18 SNPs in CACNA1C and autism in 239 trios." (PMID 26204268, 2015). "Previous genetic studies have indicated an association between autism and CACNA1C." (PMID 26566276, 2015). "Results of association analyses between two SNPs in CACNA1C and autism in 553 trios." (PMID 26204268, 2015). "Our study indicates that CACNA1C is associated with autism in Han Chinese population." (PMID 26204268, 2015). "However, several common variants in CACNA1C have also been associated with autism." (PMID 31805042, 2019). "Therefore, other gain-of-function and loss-of-function variants in CACNA1C could contribute to autism by altering axon development." (PMID 31805042, 2019). "In this family, it was therefore unclear whether the mutation in CACNA1C was causative of autism." (PMID 26386135, 2015).
autism (continued). "Results show that Cacna1c+/− rats exhibit deficits in pro-social behavior and communication together with other behavioral alterations consistent with autism-like symptoms, thus confirming a potential role of Cav1.2 in neuropsychiatric disorders." (PMID 37372947, 2023). "Here, we use egl-19, the C. elegans homolog of CACNA1C, to investigate the role of voltage-gated calcium channels in autism." (PMID 31805042, 2019). "Whereas the evidence is strongest for CACNA1C, variants in other VGCC subunit genes are also associated with autism." (PMID 31805042, 2019). "Here we report the association of two SNPs (rs1006737 and rs4765905) and haplotypes in CACNA1C with autism." (PMID 26204268, 2015). "Our research suggests that CACNA1C might play a role in the genetic etiology of autism in Chinese Han population." (PMID 26204268, 2015). "The pronounced effect of a prenatal Cacna1c depletion on emotional behavior and cognitive performance might account for its association with disorders such as SCZ and autism, which are increasingly believed to result from synaptic dysfunction during development." (PMID 28696432, 2018). "Besides TS, there is no clear evidence to date for a direct link between CACNA1C and autism." (PMID 23675382, 2013).
Hypertension (39 papers, 2013 to 2025). The presence of chronic increased pressure in the systemic arterial system. "Haplotype analysis of the candidate genes KCNJ1, NEDD4L, BDKRB2, and CACNA1C was performed to investigate the potential associations with hypertension." (PMID 39859138, 2025). "There is the same susceptibility locus of hypertension rs1006737 in the human CACNA1C gene, although the MAFs of the 2 races are different." (PMID 33663102, 2021). "Genotypes of rs1006737in CACNA1C gene and the risk of essential hypertension in Chinese Han people." (PMID 33663102, 2021). "Among the involved genes, a hypertension-candidate gene, CACNA1C, interacted with all three major genes suggesting its important role in cardiomyopathy-related hypertension." (PMID 23879630, 2013). "The dysregulation of CACNA1C may play a crucial role in the hypertension-induced endothelial dysfunction by affecting the calcium pathway." (PMID 35369349, 2022). "In addition to cardiac diseases, dysregulated Rbfox2 was recently reported to be involved in hypertension through regulating the splicing of CACNA1C exon 9* and exon 33 in arteries." (PMID 29186814, 2017). "Furthermore, genetic variants thought to be implicated in BD such as BDNF, MTHFR, GNAS, and CACNA1C/D, have been hypothesized to overlap between BD and CVD, conferring risk of mood disorders in addition to risk of hypertension, type 2 diabetes, obesity, and dyslipidemia." (PMID 30761021, 2019).